ODAD1 (outer dynein arm docking complex subunit 1)
Description:
Component of the outer dynein arm-docking complex (ODA-DC) that mediates outer dynein arms (ODA) binding onto the doublet microtubule. Involved in mediating assembly of both ODAs and their axonemal docking complex onto ciliary microtubules (By similarity).
Synonyms: CCDC114; FLJ32926; CILD20
Tractability: Small molecule: a structure with a bound ligand is known.
Gene: Protein-coding gene on chromosome 19 (48,296,355 to 48,321,971, reverse strand). Ensembl gene ENSG00000105479.
Subcellular location: Cytoplasm, cytoskeleton, cilium axoneme
Subcellular location (Human Protein Atlas): Mid piece; Connecting piece; Principal piece
Gene Ontology:
Molecular function: protein binding
Biological process: cilium movement; outer dynein arm assembly; flagellated sperm motility
Cellular component: axoneme; cilium; outer dynein arm; sperm midpiece; sperm principal piece; outer dynein arm docking complex
Genetic constraint (gnomAD): Loss-of-function variants: 43 observed, 61.33 expected, observed/expected ratio (o/e) 0.7, 90% interval 0.55 to 0.9. The upper end of that interval is the gene's LOEUF score, 0.9, which puts it in group 3 of 6, group 1 being the genes least tolerant of losing a copy. Missense variants: 875 observed, 933.97 expected, observed/expected ratio (o/e) 0.94, 90% interval 0.88 to 0.99. Synonymous variants: 337 observed, 390.67 expected, observed/expected ratio (o/e) 0.86, 90% interval 0.79 to 0.94.
Gene-disease validity (ClinGen):
ClinGen rates the evidence that ODAD1 causes each of these diseases.
primary ciliary dyskinesia 20 (autosomal recessive): Definitive.
Homologues: Orthologues: chimpanzee ODAD1 (94% identical), dog ODAD1 (70% identical), rat Odad1 (63% identical), zebrafish odad1 (23% identical), tropical clawed frog ccdc63 (22% identical). Paralogues in human: CCDC63 (19% identical), ODAD3 (12% identical), TMEM141 (2% identical).
Diseases named in the same sentence as ODAD1 in open-access papers:
ODAD1 is named in the same sentence as 14 diseases in open-access papers, as found by Europe PMC text mining. Sharing a sentence is not in itself a finding about the gene and the disease. The quoted sentences say what the papers report.
primary ciliary dyskinesia (6 papers, 2021 to 2026). A rare, genetically heterogeneous, primarily respiratory disorder characterized by chronic upper and lower respiratory tract disease. "All three groups (3D-SF, Sphere, 3D-Co) showed the down-regulation of ODAD1: a gene associated with ciliary dyskinesia." (PMID 37508868, 2023).
ciliopathy (2 papers, 2025). A genetic disorder of the cellular cilia or the cilia anchoring structures, the basal bodies, or of ciliary function. "Human LRRC56, ODAD3 and ODAD1 models were also generated and showed similar structures/folding, as well as localization of ciliopathy-associated alleles." (PMID 41229303, 2025). "Human LRRC56, ODAD3, and ODAD1 models were also generated and show similar structures/folding as well as localization of ciliopathy associated alleles." (PMID 40631331, 2025). "Importantly, mutations in ODAD3 and ODAD1 in humans are associated with motile ciliopathies, including PCD." (PMID 40631331, 2025).
situs inversus (1 paper, 2024). A congenital condition in which there is complete right-to-left reversal of the position of the major thoracic and abdominal organs (that is, they are arranged in a mirror image of the normal positioning). "Homozygous mutation in ODAD1 (CCDC114) is associated with PCD, which affects the airways in approximately 30% of patients presenting situs inversus." (PMID 38920681, 2024).
ODAD1 also shares sentences with these, for which no sentence is quoted: infertile (2 papers); Blindness (1); bronchiectasis (1); conductive hearing loss (1); Huntington disease (1); male infertility (1); Neonatal respiratory distress (1); otitis media (1); Retinal atrophy (1); sensorineural hearing loss (1); sinusitis (1).